TXNIP (thioredoxin interacting protein)
Diseases named in the same sentence as TXNIP in open-access papers (continued):
Sharing a sentence is not in itself a finding about the gene and the disease.
diabetic nephropathy (31 papers, 2014 to 2025). "In the current investigation, an analysis was conducted on twelve chemical constituents derived from MQEO in terms of their interaction with cholera toxin and the target proteins associated with diabetic nephropathy, namely, TXNIP, Nrf2, and DPP IV." (PMID 38138443, 2023). "Additionally, TXNIP has been linked to ERS‐mediated pyroptosis in diabetic nephropathy models." (PMID 39629879, 2025). "Thioredoxin-interacting protein (TXNIP) takes charge of regulating the autophagy of rats with diabetic nephropathy via the mTOR signaling pathway." (PMID 36591291, 2022). "In diabetic nephropathy, TXNIP silencing attenuated high glucose-induced apoptosis of podocyte, which was related to the inhibition of p38 MAPK and mTOR signaling pathway." (PMID 34162834, 2021). "While an axis miR-497/TXNIP has been described in diabetic nephropathy, other studies report the role of different miRNAs, including miR-17 in the TXNIP/NLRP3 signaling pathway in inflammation-induced kidney injury or brain ischemia." (PMID 33567593, 2021). "In line with these, TXNIP was also found to regulate cell autophagy in retinal Muller cells of diabetic retinopathy and renal tubular cells of diabetic nephropathy." (PMID 34162834, 2021). "With the development of diabetic nephropathy research, the significance of the Trx-TXNIP signaling system is increasingly recognized." (PMID 32456088, 2020). "TXNIP-mediated oxidative stress plays an important role in the occurrence and development of diabetic nephropathy, diabetic retinopathy, and arteriosclerosis." (PMID 32774321, 2020). "Studies have shown that TXNIP can affect the development of diabetic nephropathy by inhibiting endogenous oxidative stress." (PMID 32774321, 2020). "In wild-type and TXNIP knockout mice rendered diabetic with streptozotocin, the TXNIP knockout mice showed significant protection from diabetic nephropathy." (PMID 33302545, 2020). "Collectively, these results indicate that blockade of TXNIP suppressed the production of interstitial collagens and reduced renal interstitial fibrosis in diabetic nephropathy." (PMID 27381856, 2016). "TXNIP is significantly increased in rats and humans with diabetic nephropathy and closely correlated with urinary albumin, renal fibrosis, and reactive oxygen species." (PMID 26881256, 2016). "In the current study, we have defined the role of TXNIP in regulating tubular autophagy and mitophagy in diabetic nephropathy." (PMID 27381856, 2016). "In conclusion, our study demonstrated that upregulation of TXNIP mediates dysfunction of tubular autophagy and mitophagy through the mTOR signaling pathway and contributes to the development of diabetic nephropathy." (PMID 27381856, 2016). "Collectively these studies have demonstrated TXNIP is an important mediator of progressive tubulo-interstitial fibrosis in diabetic nephropathy." (PMID 27381856, 2016). "The present study confirms that inhibition of TXNIP by delivery of specific DNAzyme reverses the excessive extracellular matrix deposition characteristic of diabetic nephropathy." (PMID 27381856, 2016). "ROS-induced TXNIP overexpression could drive hepatic inflammation as well as lipid accumulation, diabetic retinopathy and diabetic nephropathy through activation of NLRP3 Inflammasome." (PMID 29084550, 2017). "Kidney targeted inhibition of TXNIP may be a novel therapeutic strategy for the prevention and treatment of diabetic nephropathy." (PMID 27381856, 2016). "To determine whether inhibition of TXNIP attenuates diabetic renal fibrosis via regulating tubular autophagy, we first tested whether autophagy is involved in the pathogenesis of diabetic nephropathy." (PMID 27381856, 2016). "These experiments and figures indicated that the proposed proteins in TXNIP pathway may play an important role in the inflammation of incipient diabetic nephropathy, renal sclerosis, and fibrosis." (PMID 26881256, 2016).
diabetic nephropathy (continued). "To determine whether TXNIP is involved in the pathophysiology of diabetes nephropathy, we examined the effect of modifying TXNIP expression on the development of interstitial fibrosis by measuring interstitial collagen fibril deposition using picrosirius red staining." (PMID 27381856, 2016). "Previous studies have demonstrated that elevated circulating TXNIP levels in patients with T2DM contribute to the development of diabetic peripheral neuropathy and diabetic nephropathy." (PMID 38951835, 2024). "S-adenosylhomocysteine inhibition enhanced TXNIP-mediated oxidative stress and NLRP3 inflammasome activation, which aggravated podocyte injury and diabetic nephropathy." (PMID 37814350, 2023). "It was previously reported that SS-31 protects against high-glucose-induced renal injury in diabetic nephropathy, inhibiting transforming-growth factor (TGF)-β1, NOX4, and thioredoxin-interacting protein (TXNIP)." (PMID 37371668, 2023). "The excessive TXNIP signal promotes oxidative stress and follows NLRP3 inflammasome motivation, contributing to diabetic nephropathy progression." (PMID 37229425, 2023). "In the study of diabetic nephropathy, knockdown of NLRP3 decreased the expression of thioredoxin-interacting protein and NOX4 and the production of superoxide in the diabetic kidney, and improved renal function." (PMID 35711428, 2022). "It has been reported that TXNIP is an important mediator for NLRP3 inflammasome activation, emerged as a target in multiple diseases, including cervical inflammation, diabetic nephropathy, and tubular injury." (PMID 32892306, 2021). "Thioredoxin interacting protein (TXNIP), which induces ROS production, regulated tubular autophagy and mitophagy in a rat model of diabetic nephropathy through the mTOR signaling pathway." (PMID 31382550, 2019). "NCF1, OSM, SMAD1 and TGFB1 provide protection against diabetic nephropathy, SYVM1 and TXNIP protect against diabetic retinopathy and BDNF in ameliorating the diabetic neuropathy." (PMID 28761062, 2017). "However, the interaction of TXNIP with autophagy/mitophagy in diabetic nephropathy is unknown." (PMID 27381856, 2016). "Pyroptosis mediated by thioredoxin‐interacting protein (TXNIP) aggravates diabetic kidney disease (DKD), thus clarifying the key regulator of TXNIP‐induced cell pyroptosis may delay DKD progression." (PMID 36316968, 2023). "Despite the fact that higher levels of serum TXNIP are observed in the renal tissues of diabetic kidney disease patients, drugs are currently not readily available to control DN development through the suppression of TXNIP." (PMID 38138443, 2023). "Previous studies focused on the relationship between TXNIP and DM, diabetic nephropathy and diabetic retinopathy, while there are no clinical reports on the relationship between serum TXNIP and DPN." (PMID 32774321, 2020). "Our results demonstrated that tubular autophagy is dysfunctional, as indicated by increased LC3 and P62 in kidneys of both human and rats with diabetic nephropathy, and that the dysregulated LC3 and P62 expression were normalised in the kidneys of diabetic rats treated with TXNIP DNAzyme." (PMID 27381856, 2016). "Our results firstly reveal that high glucose and lipopolysaccharide activate ROS/TXNIP/ NLRP3/IL-1β inflammasome signaling in glomerular mesangial cells, suggesting a mechanism by which inflammation may contribute to the development of diabetic nephropathy." (PMID 26881256, 2016). "Under the regulation of NOX4, TXNIP may inhibit the activation of NLRP3 inflammatory bodies by dissociating from Trx and binding with NLRP3, and PU may play a meaningful role in protection against diabetic nephropathy." (PMID 32456088, 2020).
diabetic nephropathy (continued). "In this study, we investigated the intervention effect of PU on diabetic nephropathy in a mice model induced by high-fat diet and STZ to prove the protective effect of PU on diabetic nephropathy and explore the possible mediating role taken by the TXNIP/NLRP3 pathway in the pyroptosis mechanism." (PMID 32456088, 2020). "In a diabetic kidney disease model, the lack of NOX4 and the expression of NOX5 enhanced albuminuria and renal fibrosis were enhanced, in part via TXNIP activation." (PMID 36358519, 2022).
gastric cancer (31 papers, 2014 to 2025). A primary or metastatic malignant neoplasm involving the stomach. "Knocking out the TXNIP gene in a mouse model is related to helicobacter pylori-associated gastric cancer." (PMID 35450411, 2022). "Similarly, even though high TXNIP expression is associated with favorable prognosis in breast, liver, and lung cancers, it correlates with poor prognosis in gastric cancer in a pan-cancer analysis." (PMID 37794178, 2023). "To investigate the biological role of TXNIP in gastric cancer, we employed lentiviral transduction to knock down TXNIP gene expression in AGS and HGC27 cells." (PMID 40182050, 2025). "As such, KIT inhibitors, are currently being investigated in clinical trials for their therapeutic potential in gastric cancer.TXNIP functions primarily as a molecule that binds to TRX to regulate ROS and oxidative stress within cells." (PMID 40182050, 2025). "We initially examined TXNIP protein expression levels in gastric cancer cell lines SGC7901, AGS, and HGC27, as well as in normal human gastric mucosal epithelial cells GES-1." (PMID 40182050, 2025). "In glioma cells, PTBP1 stabilizes PFKFB4 mRNA to promote glycolysis, whereas in gastric cancer cells, it accelerates the degradation of TXNIP mRNA to alleviate oxidative stress.​​." (PMID 41313521, 2025). "A Pan-cancer analysis indicated a connection between TXNIP and an unfavorable outcome in gastric cancer." (PMID 40182050, 2025). "TXNIP has a significantly reduced expression in gastric cancer tissues compared with normal tissues." (PMID 39495117, 2024). "Inhibition of miR-301b-3p or upregulation of TXNIP increased the chemosensitivity of DDP/VCR-resistant gastric cancer cells and reversed malignant behaviors." (PMID 39403600, 2024). "For example, patients with high expression of RGS4 and TXNIP exhibited a poorer prognosis in gastric cancer, while those with high expression of SLC1A5 have a better prognosis within five years." (PMID 36418919, 2022). "Low expression in TXNIP is observed in different types of cancers including breast and stomach cancers." (PMID 34497631, 2021). "Accordingly, TXNIP is downregulated in breast, bladder, and gastric cancer and in tumor transplant models TXNIP overexpression inhibits growth and metastasis." (PMID 33081035, 2020). "TXNIP overexpression in the human gastric carcinoma cell lines AGS, SNU-16, and SNU-620, the promyelocytic leukemia cell line HL-60, and HTLV-I-positive T cells led to growth reduction in vitro." (PMID 24645981, 2014). "In addition, cellular function experiments preliminarily verified the role of TXNIP in gastric cancer." (PMID 40182050, 2025). "Cellular experiments preliminarily verified that TXNIP could promote the proliferation and migration of gastric cancer cells." (PMID 40182050, 2025). "Overall, these results indicate that TXNIP exerts an oncogenic role in gastric cancer." (PMID 40182050, 2025). "Based on the datasets of the Kaplan–Meier plotter, we observed that high expression of TXNIP was associated with poor clinical outcomes of OS and PPS for gastric cancer, especially in subgroup analysis of “stage 2 to 4”, “lauren classification/intestinal/diffuse” and “treatment/surgery alone”." (PMID 35843949, 2022). "It’s worth noting that the prognostic values of TXNIP in gastric cancer were controversial." (PMID 35843949, 2022). "Interestingly, when we confined the data of gastric cancer patients with stage 2 to 4 disease, patients with lymph node metastasis, and patients treated with surgery alone, a correlation between decreased TXNIP and good survival outcomes was observed." (PMID 35843949, 2022). "Moreover, low TXNIP expression is reported as a potent prognostic biomarker for gastric cancer recurrence." (PMID 32511893, 2020).
gastric cancer (continued). "In addition, an increased incidence of HP-induced gastric cancer was reported in TXNIP knockout mice, and TXNIP mRNA expression in gastric cancer tissues of patients was significantly lower than that in surrounding normal tissues[26‒27]." (PMID 30008463, 2018). "Analogously, microRNA-301b-3p from mesenchymal stem cells (MSCs) is delivered to chemotherapy-sensitive cells via exosomes to promote gastric cancer (GC) resistance by targeting TXNIP." (PMID 39135913, 2024). "The expression level of TXNIP was meaningfully lower in gastric cancer (GC) tissues compared with normal tissues, TXNIP negatively regulates helicobacter pylor-related GC by inhibiting TNFα-induced activation of NF-κB signaling pathway." (PMID 35450411, 2022). "In gastric cancer datasets, MT2A, TXNIP, FOS, RHOB, and GLUL emerged as the five most important mRNAs to predict exmiRs." (PMID 39495117, 2024). "As well, TXNIP expression was lower in stomach cancer compared with the normal gastric samples, consistent with boxplot analysis." (PMID 37037466, 2023). "Similarly, LINC01089 inhibits gastric cancer cell growth by targeting miR‐27a‐3p and enhancing TET1 expression, and STARD7‐AS1 has been reported to modulate cell proliferation and autophagy through the miR‐31‐5p/TXNIP." (PMID 40665897, 2025).
endothelial dysfunction (30 papers, 2017 to 2025). In vascular diseases, endothelial dysfunction is a systemic pathological state of the endothelium (the inner lining of blood vessels) and can be broadly defined as an imbalance between vasodilating and vasoconstricting substances produced by (or acting on) the endothelium. "The TXNIP pathway partially mediates endothelial dysfunction, and the TXNIP level is associated with the progression of endothelial dysfunction." (PMID 35450411, 2022). "In their study, MAPK/TXNIP (thioredoxin interacting protein signaling) is positively involved in CSE/H2S deficiency-associated endothelial dysfunction." (PMID 36034427, 2022). "We further showed that exercise training ameliorated ER stress-associated endothelial dysfunction in coronary arterioles in ApoE KO mice by reducing ER stress and TXNIP/NLRP3 inflammasome signaling." (PMID 34326395, 2021). "The decreased expression of TRX, associated with increased expression of TXNIP, is implicated in endothelial dysfunction associated with aging and, in this context, increased expression of NADPH oxidase is also reported." (PMID 33567593, 2021). "Also, we hypothesized that exercise training would alleviate ER stress-associated endothelial dysfunction in atherosclerotic coronary arterioles by reducing ER stress signaling and its downstream cascade including TXNIP/NLRP3 inflammasome." (PMID 34326395, 2021). "Moreover, knowing TXNIP involvement in ROS production and inflammation, which leads to endothelial dysfunction, TXNIP may also be implicated in vessel damage." (PMID 33567593, 2021). "On one hand, TMAO can stimulate inflammation and endothelial dysfunction by activating the reactive oxygen species/thioredoxin-interacting protein (TXNIP)/NOD-like receptor family pyrin domain-containing 3 (NLRP3) inflammasome pathway." (PMID 40821112, 2025). "The suppression of TXNIP/NLRP3 inflammasome can abrogate endothelial dysfunction, conferring neuroprotection in an ischemic stroke model." (PMID 38747733, 2024). "Their research indicates that in the context of CSE/H2S deficiency-associated endothelial dysfunction, the MAPK/TXNIP (thioredoxin interacting protein) signaling pathway plays a pivotal role." (PMID 39156383, 2024). "We conclude that TXNIP upregulation contributes to low-magnesium-induced endothelial dysfunction in vitro." (PMID 37176057, 2023). "In vitro TXNIP is increased in hypertension-promoted endothelial dysfunction and in 4-hydroxynonenal-induced endothelial senescence." (PMID 37176057, 2023). "In summary, our data suggested TXNIP playing an important role in vascular inflammation, oxidative metabolism and mitochondrial dysfunction, with respect to endothelial dysfunction development." (PMID 36465470, 2022). "Among H2S-targeted proteins involved in hypertension-resulted endothelial dysfunction are thioredoxin interacting protein (TXNIP), MAPK, and eNOS." (PMID 36358508, 2022). "Collectively, these data suggest that disturbed flow led to a significant TXNIP expression increase, resulting in endothelial dysfunction." (PMID 36465470, 2022). "Our data demonstrated that TXNIP plays an important role in the development of endothelial dysfunction." (PMID 36465470, 2022). "Conversely, TXNIP has a pro-inflammatory role leading to cardiac, vascular and endothelial dysfunctions." (PMID 33567593, 2021). "Metformin or other compounds are also used to lower TXNIP aortic levels in vivo or endothelial levels in vitro in order to restrain NLRP3 activation and protect from endothelial dysfunction and cardiovascular risk factors." (PMID 33567593, 2021). "Our results are in keeping with the increasing evidence pointing to upregulated TXNIP as a player in endothelial dysfunction in response to high glucose levels." (PMID 34944690, 2021). "Focusing on the endothelium, TXNIP is overexpressed in the vascular EC of many vessels in hypertensive rats and contributes to oxidative stress and endothelial dysfunction in hypertension." (PMID 34944690, 2021).